MIB1 (MIB E3 ubiquitin protein ligase 1)
Diseases named in the same sentence as MIB1 in open-access papers (continued):
Sharing a sentence is not in itself a finding about the gene and the disease.
acute pancreatitis (1 paper, 2022). An acute inflammatory process that leads to necrosis of the pancreatic parenchyma. "In conclusion, during the process of acute pancreatitis, MIB1 downregulation led to ASAH1 upregulation, resulting in pyruvate kinase inhibition, followed by trypsinogen activation." (PMID 36068514, 2022). "Exogenous MIB1 diminished the elevation in trypsin activity induced by acute pancreatitis inducer." (PMID 36068514, 2022). "MIB1/ASAH1/sphingosine/pyruvate kinase axis regulated trypsinogen activation in acute pancreatitis." (PMID 36068514, 2022). "Additionally, E3 ligase MIB1 decreased in acute pancreatitis, resulting in the inhibition of the proteasome degradation of ASAH1." (PMID 36068514, 2022). "Additionally, E3 ligase Mind bomb homolog 1 (MIB1) decreased in acute pancreatitis resulting in the decreased binding between MIB1 and ASAH1." (PMID 36068514, 2022). "Therefore, MIB1 downregulation in acute pancreatitis may presumably be related to calcium overload." (PMID 36068514, 2022).
allergies (1 paper, 2012). "Furthermore, our results suggest that Mib1 is a latent therapeutic target for the regulation of Notch activation in disorders caused by a predominance of Th2 cell-cytokines, such as allergies, asthma, atopic dermatitis, systemic lupus erythematosus, and chronic graft-versus-host disease." (PMID 22558446, 2012).
anal carcinoma (1 paper, 2010). "Four studies have investigated the association between cellular proliferation in anal carcinoma as determined by the Ki-67/MiB1 index and clinical outcome." (PMID 21063399, 2010). "Data from two of the four studies of Ki-67/MiB1 supported a predictive role in the prognosis of anal cancer patients treated with chemoradiotherapy." (PMID 21063399, 2010).
anaplastic meningioma (1 paper, 2012). A WHO grade III meningioma characterized by the presence of malignant morphologic features, including malignant cytology and a very high mitotic index (20 or more mitoses per ten high power fields). "Expression of proliferation markers, such as MIB-1 and Ki-67, has generally shown progressive increases in the labeling index with a WHO grade from 1.00-1.35% for grade I to 1.90-9.30% for grade II or atypical meningiomas and 5.60-19.5% for grade III or anaplastic meningiomas." (PMID 22264362, 2012).
angiosarcoma (1 paper, 2022). A malignant tumor arising from the endothelial cells of the blood vessels.
Atrophy (1 paper, 2021). Any weakening or degeneration, especially through lack of use. "The decrease in Mib1 or accumulation of Actn3 in skeletal muscle with age represents as a therapeutic target to treat or ameliorate age-associated muscle atrophy." (PMID 33637766, 2021).
autism (1 paper, 2025). Persistent deficits in social interaction and communication and interaction as well as a markedly restricted repertoire of activity and interest as well as repetitive patterns of behavior. "Finally, in 82 patients, we identified variants in 14 genes, such as RELN, KATNAL2, MIB1, associated with autism susceptibility, with low penetrance or with limited information about their involvement in NDDs." (PMID 40019509, 2025).
Bicuspid aortic valve (1 paper, 2024). The presence of an aortic valve with two instead of the normal three cusps (flaps). "Heterozygous Gata6 loss-of-function mutations alone or humanized Mib1 mutations in a NOTCH1-sensitized genetic background cause bicuspid aortic valve (BAV) and a membranous ventricular septal defect (VSD), consistent with MIB1 and NOTCH1 functioning in the same pathway." (PMID 39057643, 2024).
bone osteosarcoma (1 paper, 2025). A usually aggressive malignant bone-forming mesenchymal neoplasm arising from the bone. "We used human bone osteosarcoma cells (U2OS) from which MIB1 was knocked out as sender cells (MIB1-KO cells)." (PMID 41174261, 2025).
brain glioma (1 paper, 2023). A malignant glioma that involves the brain. "IVIM biexponential parameters were recently discussed about the correlations between IVIM-derived fast diffusion and perfusion fraction parameters and VEGF- and MIB-1-positive rates in brain gliomas." (PMID 37182187, 2023).
breast tumors (1 paper, 2014). "MIB-1 was positive in 63 (63.6%) of 99 ER negative breast tumors, however, this was found not to be significant." (PMID 24586570, 2014).
Burkitt lymphoma (1 paper, 2025). A rare form of malignant mature B-cell non-Hodgkin lymphoma. "Postsurgical histopathological analysis confirmed the diagnosis of Burkitt lymphoma, characterized by diffuse infiltration of medium-sized lymphocytes, a high MIB1 proliferation index, and Myc gene rearrangement." (PMID 40295232, 2025).
carcinoid tumor (1 paper, 2022). A slow growing neuroendocrine tumor, composed of uniform, round, or polygonal cells having monotonous, centrally located nuclei and small nucleoli, infrequent mitoses, and no necrosis. "Biopsy results from the initial admission characterized the obstructing infrahilar mass as a carcinoid tumor with positive synaptophysin/ chromogranin stain and low proliferation (Mib1 < 2%)." (PMID 36579277, 2022).
chordoma (1 paper, 2018). Chordomas are rare malignant tumors arising from embryonic remnants of the notochord in axial skeleton. "In all cases, diagnoses of chordoma were confirmed by histopathology, with no or very low mitotic activity apparent in hematoxylin and eosin-stained sections or a proliferation index of 1 ± 5% as estimated by anti-Ki67 (MIB1) immunostaining." (PMID 30200131, 2018).
colon cancer (1 paper, 2023). "We show that one of the important epigenetic markers, H2AK119ub is regulated by SET/TAF-Iβ-MIB1 ubiquitinating complex in various cancers including colon cancer in PRC1-independent mechanism." (PMID 37746636, 2023). "Together, our study reveals a novel PRC1-independent epigenetic regulatory mechanism for H2AK119ub by SET/TAF-Iβ and MIB1 in colon cancer." (PMID 37746636, 2023). "Analysis of data from the GENT2 database revealed that MIB1 expression is elevated in colon cancer as compared with healthy colon tissues." (PMID 37746636, 2023). "All together, these findings suggest that SET/TAF-Iβ and MIB1 might provide novel mechanism for identifying therapeutic targets for colon cancer." (PMID 37746636, 2023). "Notably, expression levels of MIB1 were found to be positively correlated with colon cancer stages when analyzed with cBioPortal." (PMID 37746636, 2023). "Taken together, our data suggest that MIB1 acts as a novel binding partner of SET/TAF-Iβ to form ubiquitination complex and the complex has roles in regulating gene expressions at the transcriptional level through histone modification in colon cancer." (PMID 37746636, 2023).
cyst (1 paper, 2017). A sac-like closed membranous structure that may be empty or contain fluid or amorphous material. "Ki-67/Mib1 positive cells were present not only in all cells of the basal layer but also focally in the middle layer of the cyst epithelia." (PMID 29410959, 2017).
cystadenoma (1 paper, 2017). A benign or borderline cystic epithelial neoplasm arising from the glandular epithelium. "In our previous study of BRCA1 and MIB-1 expression in ovarian epithelial tumors, we found that BRCA1 was highly correlated with MIB-1 expression in cystadenomas and borderline tumors." (PMID 28270171, 2017).
dysplasia (1 paper, 2007). A usually neoplastic transformation of the cell, associated with altered architectural tissue patterns. "Our aim was to assess the immunohistochemical expression of hypoxia-inducible factor (HIF)-1α, HIF-2α, erythropoietin (Epo), Epo receptor (Epo-R), Glut-1 and vascular endothelial growth factor (VEGF) along with Ki67/MIB-1 in the Barrett's metaplasia–dysplasia–adenocarcinoma sequence." (PMID 17437013, 2007).
emphysema (1 paper, 2005). "Similar numbers of MIB1-positive alveolar septal cells were observed in both types of emphysema and control lungs (1.7 ± 1.1)." (PMID 15705190, 2005).
endometriosis (1 paper, 2025). The growth of functional endometrial tissue in anatomic sites outside the uterine body. "MIB1 expression was higher in cancer and atypical endometriosis but not significant (p = 0.073)." (PMID 40364006, 2025).
ependymoma (1 paper, 2014). A WHO grade II, slow growing tumor of children and young adults, usually located intraventricularly. "The tumor was diagnosed as an anaplastic ependymoma, WHO grade III with low-grade mitosis-poor areas and high cellular tissue with mitosis and high MIB-1 rate." (PMID 25144312, 2014).
familial cancers (1 paper, 2013). "When VEGF was related with clinicopathologic characteristics, we found that in familial cancers VEGF expression was significantly associated with poor tumor grade and MIB-1 positive expression, confirming the close relationship with cancer progression." (PMID 23326384, 2013). "VEGF immunoreactivity was correlated with poor tumor grade (p = 0.0074), hormone receptors negativity (p = 0.0206, p = 0.0002 respectively), and MIB-1-labeling index (p = 0.0044) in familial cancers (BRCA1-2 and BRCAX)." (PMID 23326384, 2013).
gastrointestinal stromal tumor (1 paper, 2013). "The histopathology of the resected specimen was consistent with a gastrointestinal stromal tumor of the stomach (positive for CD 117) with a high risk of malignancy (mitotic count >5/50 high-power fieldand Ki67/Mib1 >10%)." (PMID 23914945, 2013).
glomus tumor (1 paper, 2018). A rare benign or malignant mesenchymal neoplasm arising from cells that resemble the modified smooth muscle cells of the glomus body.
hepatocellular carcinoma (1 paper, 2011). A malignant tumor that arises from hepatocytes. "Some clinicopathological studies have identified positive correlations between nuclear survivin expression and various parameters of growth fraction (MIB-1, PCNA and mitotic indices) in hepatocellular carcinoma [reviewed in 4]." (PMID 22075440, 2011).
laryngeal tumour (1 paper, 2006).
liver PEComa (1 paper, 2023). "In contrast, the rates of occurrence of high MIB-1 index values (> 10%) were 13% (1/8) in skin PEComa, 0% (0/12) in pancreatic PEComa, and 4% (1/26) in liver PEComa." (PMID 37470853, 2023).
malignant meningioma (1 paper, 2016). "We report that MIB-1 index >8% was significantly associated with worse OS and RFS in patients with atypical or malignant meningioma." (PMID 27760993, 2016).
malignant peripheral nerve sheath tumor (1 paper, 2025). Malignant peripheral nerve sheath tumor (MPNST) is a rare and often aggressive soft tissue sarcoma occurring in a wide range of anatomical sites. "Approximately 1% of the tumor cells were S100+, CD34+, SOX10+, and MIB-1 positive, and the growth was diagnosed as a myxoid low-grade malignant peripheral nerve sheath tumor (MPNST)." (PMID 40777560, 2025).
mesenchymal tumors (1 paper, 2021). "A differential diagnostic method with IHC staining using a combination of several monoclonal antibodies against LMP2/β1i and other candidate cellular factors, such as caveolin 1, cyclin B, cyclin E, Ki-67/MIB1, and CD44, has been investigated for uterine mesenchymal tumors, including uLMS." (PMID 34563053, 2021).
multiple myeloma (1 paper, 2015).
muscle atrophy (1 paper, 2021). The loss of muscle tissue due to inactivity or disease. "In addition, we further suggest that the maintenance of type 2 glycolytic myofibers via the Mib1–Actn3 axis might serve well as a therapeutic target for age-associated muscle atrophy and will broaden our understanding of the disease." (PMID 33637766, 2021). "Thus, our findings on Mib1-dependent accumulation of Actn3 with age will expand the understanding of how age-associated regulation of sarcomeric proteins is implicated in age-associated muscle atrophy." (PMID 33637766, 2021).
myeloproliferative neoplasm (1 paper, 2020). A clonal hematopoietic stem cell disorder, characterized by proliferation in the bone marrow of one or more of the myeloid (i.e., granulocytic, erythroid, megakaryocytic, and mast cell) lineages. "When Mindbomb-1 (Mib1), an essential gene for Notch ligand endocytosis, was deleted (Mx1-cre; Mib1−/− mice or MMTV-cre, Mib1−/−1 mice), the mice developed de novo myeloproliferative neoplasm (MPN), which is attributable to the loss of Mib1 from the bone marrow microenvironment." (PMID 33585446, 2020).
neuroendocrine pancreatic cancer (1 paper, 2014). "MIB-1 (directed against the Ki-67 antigen) helps to determine neuroendocrine pancreatic cancer grade and prognosis." (PMID 24641834, 2014).
neurofibroma (1 paper, 2007). An intraneural or extraneural neoplasm arising from nerve tissues and neural sheaths. "The absence of cytological features like pleomorphism and mitosis with increase in proliferation markers (MIB1) would help in ruling out malignancy and avoid misinterpretation of FMGCs in neurofibromas." (PMID 18067673, 2007).
non-compaction cardiomyopathy (1 paper, 2014). Left ventricular non-compaction (LVNC) is characterized by prominent left ventricular trabeculae and deep inter-trabecular recesses. "We identified our patient to have a sequence variant in the MIB1 (mindbomb E3 ubiquitin protein ligase 1) gene which has been linked to non-compaction cardiomyopathy." (PMID 24669931, 2014). "The sequence variant in the MIB1 gene for example raises suspicion that the non-compaction cardiomyopathy could be related to dysfunction in this gene and may or may not be related to the GARS gene dysfunction." (PMID 24669931, 2014).
non-small cell lung carcinoma (1 paper, 2022). A group of at least three distinct histological types of lung cancer, including non-small cell squamous cell carcinoma, adenocarcinoma, and large cell carcinoma. "In addition, MIB1 ubiquitin ligase facilitates NRF2 degradation resulting in ferroptosis in response to inducers, but USP11 deubiquitinating enzyme reverses this process leading to increased NRF2 protein stability in non-small cell lung cancer (NSCLC)." (PMID 36289191, 2022).
Obesity (1 paper, 2024). Accumulation of substantial excess body fat. "As the changes of Notch signaling have been reported in AD brain, the increase of MIB1 in HFSD may be involved in obesity-induced cognitive changes." (PMID 38542534, 2024).
oral squamous cell carcinomas (1 paper, 2020). "Finally, we tested our digital framework on a case series of oral squamous cell carcinomas (OSCC), arranged in tissue microarrays; we selected two consecutive sections of each OSCC FFPE TMA (tissue microarray) block, respectively stained with H&E and immuno-stained for Ki67/MIB1." (PMID 32466184, 2020).
osteosarcoma (1 paper, 2008). A usually aggressive malignant bone-forming mesenchymal neoplasm, predominantly affecting adolescents and young adults.
ovarian epithelial tumor (1 paper, 2017). A benign, borderline, or malignant tumor that originates from the surface epithelium of the ovary. "If we believe that ovarian epithelial tumorigenesis is a multi-step process, our finding that high correlation of BRCA1 and MIB-1 in OEIs supports the assumption that ovarian epithelial tumors at least some of them may arise from OEIs." (PMID 28270171, 2017).
parathyroid adenoma (1 paper, 2014). "Also consistent with the diagnosis of atypical parathyroid adenoma is the low number of cells staining for Ki-67 and MIB-1." (PMID 24959180, 2014).
Parkinson disease (1 paper, 2022). A progressive degenerative disorder of the central nervous system characterized by loss of dopamine producing neurons in the substantia nigra and the presence of Lewy bodies in the substantia nigra and locus coeruleus. "In conclusion, lncZFAS overexpression inhibited the TXNIP/MIB1 E3 ubiquitin ligase/NLRP3 pathway through direct interference with miR590-3p, which shows a novel research avenue in exploring the mechanism of inflammasome activation and pyroptosis in Parkinson’s disease." (PMID 34775541, 2022).
Patent ductus arteriosus (1 paper, 2018). In utero, the ductus arteriosus (DA) serves to divert ventricular output away from the lungs and toward the placenta by connecting the main pulmonary artery to the descending aorta. "Taken together with our functional data that the p.Q237H mutation causes relatively mild damage to MIB1 function, it might explain why this patient has a relatively mild form of CHD, which is a patent ductus arteriosus." (PMID 30322850, 2018).
pilomatrixoma (1 paper, 2008). Pilomatrixoma is a rare and benign hair cell-derived tumor occurring mostly in young adults (usually under the age of 20) and characterized as a 3-30 mm solitary, painless, firm, mobile, deep dermal or subcutaneous tumor, most commonly found in the head, neck or upper extremities. "Fayyazi and colleagues have assessed expression of the cell proliferation associated antigen Ki 67 (MIB1) in 15 pilomatrixomas." (PMID 19040752, 2008).
pituitary carcinomas (1 paper, 2016). A primary or metastatic malignant neoplasm affecting the pituitary gland. "A MIB1 LI score of >10% is equally typical for pituitary carcinomas." (PMID 26811407, 2016).
plasmacytoma (1 paper, 2015). Plasmacytoma is a localized mass of neoplastic monoclonal plasma cells that represents approximately 5% of all plasma cell neoplasms. "Additional immunostaining test results were negative for CD56 and showed high MIB-1 expression in the extramedullary plasmacytoma and low MIB-1 expression in the bone marrow." (PMID 25880694, 2015). "An immunohistochemical analysis was negative for CD56 and showed high MIB-1 expression in the extramedullary plasmacytoma and low MIB-1 expression in the bone marrow, contributing to the potential underlying pathophysiology of the recurrent extramedullary plasmacytomas and their genetic changes." (PMID 25880694, 2015).
renal carcinoma (1 paper, 2022). A carcinoma arising from the epithelium of the renal parenchyma or the renal pelvis. "In addition, Ki-67 can be used in combination with other markers such as MCM-2, survivin, B7-H1, geminin, carbonic anhydrase, IX, gelsolin, MIB-1, and phosphorylated S6 protein, and the interaction between white (pS6) and vimentin affects the prognosis of renal cancer." (PMID 35741311, 2022).
retinoblastoma (1 paper, 2013). A malignant tumor that originates in the nuclear layer of the retina. "In our previous study, high MIB-1 LI expression levels were associated with poor prognosis in retinoblastomas, and the increased expression of HMGA1 and HMGA2 correlated with the MIB-1 LI." (PMID 23935884, 2013).